HIF1A (hypoxia inducible factor 1 subunit alpha)
Diseases named in the same sentence as HIF1A in open-access papers (continued):
Sharing a sentence is not in itself a finding about the gene and the disease.
glioblastoma (continued). "Pseudopalisading cells surrounding necrotic regions in glioblastoma are characterized by HIF-1α accumulation and upregulation of hypoxia-inducible genes that drive angiogenesis, mesenchymal transition, and invasion." (PMID 41331572, 2025). "Our findings suggest that FDX1 acts as an upstream factor, regulating DNA-PKcs and modulating HIF-1α expression levels through distinct pathways in glioblastoma cells under severe hypoxia." (PMID 40244269, 2025). "Hypoxia in glioblastoma enhances immunosuppression by upregulating HIF1α, which drives legumain (LGMN) expression in TAMs." (PMID 40223940, 2025). "Studies have shown that HIF1α and HIF2α orchestrate several cellular processes that are crucial for the pathogenesis of glioblastoma." (PMID 38893207, 2024). "Elevated levels of nuclear-localized HIF-1α are found in most glioblastomas and anaplastic astrocytomas, particularly near necrotic areas in glioblastomas." (PMID 39795182, 2024). "A plethora of studies clarify the different roles of HIF1α in the progression of glioblastoma and response to treatment." (PMID 38893207, 2024). "Menadione, a ROS-inducing agent, has been shown to decrease HIF-1α target gene expression and induce cell death in glioblastoma cells." (PMID 39273204, 2024). "This signaling pathway exerts a profound influence on the progression of glioblastoma and modulates important cellular processes such as migration, invasion, and the expression of HIF1α." (PMID 38893207, 2024). "The administration of OMX in mice with individual orthotopic glioblastoma tumors resulted in a reduction of over 50% in the hypoxic tumor area, as evidenced by immunostaining with glucose transporter 1 (Glut1) and HIF-1α markers." (PMID 38741109, 2024). "Circadian and HIF-1α pathways can enhance carcinogenesis and tumor progression in glioblastoma and renal carcinoma." (PMID 38534356, 2024). "As hypoxia activation was positively correlated with RAS receptor expression, the association with HIF1A and RAS gene expression was investigated after glioblastoma cell lines were treated with chemoradiation." (PMID 38607073, 2024). "It was recently reported that hypoxia-induced ROS augment the hypoxic adaptation of glioblastoma by mediating the HIF-1α-SERPINE1 signaling pathway, making ROS a promising therapeutic target for glioblastoma." (PMID 38520006, 2024). "In glioblastoma cells, elevated ROS levels can disrupt the protein–protein interactions between HIF-1α and the transcriptional co-activator p300, which prevents the activation of HIF-1α target genes and subsequent tumor growth." (PMID 39273204, 2024). "A previous study identified a positive feedback loop consisting of p21/HIF-1α that exacerbates radioresistance in glioblastoma cells by promoting Glut1/LDHA-mediated glycolysis." (PMID 38778409, 2024). "In the field of glioblastoma therapy, various targeted and systematic approaches have emerged to target the complex signaling pathways mediated by HIF1α." (PMID 38893207, 2024). "Several drugs targeting HIF1α and related signaling pathways have been evaluated for their effects on glioblastoma." (PMID 38893207, 2024). "In glioblastoma, Icaritin inhibits EMT in the glioblastoma (GBM) cell line U87MG in a PTEN/Akt/HIF-1α pathway." (PMID 38255995, 2024). "Its role in inflammation has only recently been described within the context of neurological disorders, such as glioblastoma multiforme, where it was shown to be important to the hypoxia-inducible factor 1α (HIF1α) inflammation axis." (PMID 38912581, 2024). "HIF-1α protein was expressed in the nuclei of most glioblastoma cells, especially around the necrotic zone of glioblastoma." (PMID 38734702, 2024). "The aim of this study was to evaluate a wide range of potential prognostic factors, including HIF-1α and hemoglobin levels, for survival in glioblastoma." (PMID 38927417, 2024).
glioblastoma (continued). "HIF-1α-positive glioblastoma tumors exhibit a significant co-localization of VEGF and PDGF-C within their cells, highlighting a strong correlation between these factors and HIF-1α activity." (PMID 38542288, 2024). "NOX4-derived ROS arbitrates TGF-β1-induced metabolic reprogramming during EMT via PI3K/AKT/HIF-1α pathway in glioblastoma." (PMID 38720270, 2024). "PFKFB3 is a target gene of HIF-1α in response to hypoxia in human glioblastoma cell lines and mouse embryonic fibroblasts, thereby providing another mechanism by which HIF-1α promotes glycolysis." (PMID 37020557, 2023). "Tumor oxygenation is commonly disturbed in glioblastomas resulting in hypoxia that activates the hypoxia-inducible factor, HIF1-α, which in turn supports glioblastoma progression and invasiveness." (PMID 36644500, 2023). "The stabilization of HIF-1α in a hypoxic cellular condition depends on the generation of glioblastoma mitochondrial reactive oxygen species (ROS)." (PMID 37107298, 2023). "HIF1α, a transcription factor in the VEGF signaling pathway appears to be an integral component of this recruitment as HIF1α-deficient glioblastoma tumors displayed low BMDCs and severely impaired angiogenesis." (PMID 36765787, 2023). "Their data showed that miR-93 was downregulated in human glioblastoma cell lines, and restoration of miR-93 levels in glioblastoma cells led to a decreased expression of an array of inflammatory genes (HIF-1α, MAP3K2, IL-6, G-CSF, IL-8, LIF, and IL-1β)." (PMID 38239396, 2023). "In conclusion, we discovered the role of KDELC2 in inducing glioblastoma angiogenesis via the activation of ROS and HIF-1α." (PMID 37107298, 2023). "KDELR2 is a poor prognostic factor for glioblastoma and acts as a direct target of HIF-1α, a regulator of p-mTOR as well as the downstream protein in glioblastoma cells." (PMID 36096734, 2022). "It is known that the suppression of HIF-1α has been investigated to sensitize glioblastoma cells to temozolomide (TMZ) treatment." (PMID 36157351, 2022). "To do this, we identified a group of tumors (n = 28) with a high level of the HIF-1α hypoxic marker and a group (n = 26) with a low expression of this marker among the glioblastomas." (PMID 36612140, 2022). "Here we present data from 37 human glioblastoma tissue samples analysed for ascorbate content and protein levels of HIF-1α and selected down-stream targets, along with patient clinical information and follow-up data." (PMID 35419292, 2022). "To functionally investigate the impact of KDM5C overexpression on the BDNF and HIF1A levels, we transiently transfected the T98G glioblastoma cell line with KDM5C plasmid." (PMID 36142158, 2022). "In the patients with glioblastoma, HIF-1α promoted tumor stemness and self-renewal, and inhibited differentiation, which was associated with the disease progression." (PMID 36091021, 2022). "Recently, it has been reported that the PI3K/Akt/mTOR/HIF-1α pathway is involved in enhancing the migration and invasion of human glioblastoma cells under hypoxia." (PMID 35360199, 2022). "Activation of HIF-1α and HIF-1α (EPAS1) expressions in glioblastoma stem-like cells has been observed." (PMID 36307808, 2022). "PKM2 activates the HIF-1α/PKM2 feedforward loop and maintains HIF-1α protein stability in fibroblast and glioblastoma cells through activation of various proliferative and angiogenic signaling pathways." (PMID 35967360, 2022). "HIF-1α levels after RT in glioblastoma patients were significantly higher than meningioma patients (p3 < 0.001)." (PMID 36121548, 2022). "The study findings elucidate a mechanism whereby LSD1 controls senescence in Glioblastoma tumor cells through the regulation of HIF-1α, and their propose the novel defined LSD1/HIF-1α axis as a new target for the therapy of Glioblastoma tumors." (PMID 35042538, 2022).
glioblastoma (continued). "While both appear to have a positive impact on expression in ovarian cancer, HIF1α appears to play an inhibitory role on TUBB3/βIII-tubulin expression in glioblastoma cells." (PMID 35573698, 2022). "Protease inhibitors have been shown to downregulate vascular endothelial growth factor (VEGF) and hypoxia-inducible-factor (HIF)-1a expression in glioblastoma cells." (PMID 35978755, 2022). "The current study revealed a significant increase in serum HIF-1α in glioblastoma (GB) subgroup either prior to or following RT in comparison to healthy volunteers." (PMID 36121548, 2022). "Statistical analysis showed a significant increase in serum HIF-1α in glioblastoma subgroup either prior to or following RT in comparison to healthy volunteers (p1 < 0.001and < 0.001 respectively)." (PMID 36121548, 2022). "In glioblastoma patients pre-RT, the mean ± SD of serum HIF-1α was 2.61 ± 1.94 that was increased to 4.34 ± 3.30 post-RT, while it was 1.41 ± 0.32 in healthy controls." (PMID 36121548, 2022). "In glioblastoma hypoxia reduced HIF1α expression, leading to HIF2α binding to the two overlapping HREs located in the 3′UTR of the gene." (PMID 35573698, 2022). "In glioblastoma, CSCs of the peri-necrotic zone, expressing HIF-1α, harbor a quiescent phenotype highlighted by the suppression of the RNA polymerase II phosphorylation at serine 2 (RNApII-S2P), a marker of transcriptionally less active quiescent cells." (PMID 34539584, 2021). "More interestingly, knocking down HIF-1α concurrently lowered CoCl2-induced autophagic insults to human TMZ-resistant glioblastoma cells." (PMID 34136065, 2021). "This study suggested that hypoxia, partly through the activation of HIF-1α, played an important role in the differentiation of glioblastoma stem cells to endothelial cells." (PMID 33946480, 2021). "As a result, one possible mechanism explaining CoCl2-induced autophagy of human drug-resistant glioblastoma cells is via triggering HIF-1α-dependent mitochondrial autophagy." (PMID 34136065, 2021). "Fascinatingly, exposure to CoCl2 time-dependently raises levels of HIF-1α in drug-resistant glioblastoma cells." (PMID 34136065, 2021). "Other studies have shown that inhibition of PI3K/Akt/mTOR pathway and HIF-1α can inhibit the migration and invasion of human glioblastoma U87 cells." (PMID 34917504, 2021). "In line with our proposed HIF1α—Gal3-associated mechanism for K-Ras selectivity, others have shown that elaiophylin decreases HIF1α expression in U87MG glioblastoma cells and sensitized SKOV3 ovarian cancer cells to hypoxia." (PMID 34199986, 2021). "At the same time, roles of HIF-1α in CoCl2-induced autophagy of human drug-resistant U87 MG-R glioblastoma cells were further investigated." (PMID 34136065, 2021). "Exposure to CoCl2 for 6, 12, and 24 h caused respective 2.4-, 2.9-, and 3.8-fold increases in levels of HIF-1α in human U87 MG-R glioblastoma cells." (PMID 34136065, 2021). "The HIF-1α levels in mouse GL261-R glioblastoma cells increased 3.6-fold following treatment with 100 μM CoCl2 for 24 h." (PMID 34136065, 2021). "Hypoxia induced by CoCl2 can trigger autophagy of human and murine drug-resistant glioblastoma cells via a HIF-1α-dependent pathway." (PMID 34136065, 2021). "Exposure of human and mouse TMZ-resistant glioblastoma cells to CoCl2 increased HIF-1α levels and induced hypoxic stress and insults." (PMID 34136065, 2021). "For example, hypoxia maintains CD133-positive glioblastoma cells in an undifferentiated state and enhances their self-renewal activity through a HIF-1α dependent way." (PMID 34539584, 2021). "Recent research has found that HIF-1α is activated via the Akt/mTOR pathway, enhancing the migration and invasion of human glioblastoma U87 cells." (PMID 32685545, 2020).
glioblastoma (continued). "Hypoxia-inducible factor 1-alpha (HIF-1α) directly promotes H19 expression under hypoxia in glioblastoma cells." (PMID 32650527, 2020). "In summary, both HIF1α and HIF2α regulate glioblastoma cell proliferation, dedifferentiation and chemoresistance through a specific pathway, which is important for glioblastoma treatments." (PMID 33208727, 2020). "For instance, HIF1α downregulation contributed to the suppression of radioresistance of glioblastoma cells." (PMID 33304897, 2020). "DGKα knockdown decreased both total and phosphorylated forms of mTOR, hypoxia-inducible factor 1-alpha (HIF1α), c-Myc levels, and phosphorylation of Akt in glioblastoma cells." (PMID 32722576, 2020). "Research has shown that PINK1 can work as a regulator of the Warburg effect and a negative regulator of glioblastoma growth, and the loss of PINK1 contributes to the Warburg effect through ROS-dependent stabilization of HIF1A." (PMID 33244455, 2020). "Bao and colleagues studied G9a and GLP catalyzed induction of the HIF1α-K674me1/2 proteoform within the context of glioblastoma cell migration." (PMID 33088284, 2020). "Briefly, in a hypoxic microenvironment the HIF1α/HIF2α-miR210-3p network promotes the malignant progression of glioblastoma through a positive feedback loop with EGF." (PMID 33208727, 2020). "In fact, AMPK activation promotes glioblastoma growth by inducing lipid internalization and sustains bioenergetics of glioblastoma through HIF-1α signaling." (PMID 31781355, 2019). "This is consistent with a previous finding, where downregulation of NRF-2 expression via shRNA interference impaired the hypoxia-mediated induction of HIF-1α and its target gene expression in glioblastoma cells." (PMID 31527445, 2019). "HIF-1α silencing is also effective to decrease invasive potential and rise chemosensitivity of human glioblastoma (LN229) and astrocytoma (U-251MG) cell lines to temozolomide, and to potentiate sorafenib-mediated apoptosis in HCC cells." (PMID 31835431, 2019). "Consistently, increased ROS during cyclic hypoxia (0.5–1% O2, 1 h hypoxia; 30 min reoxygenation; 3 cycles) upregulated HIF-1α and NF-κB expression in glioblastoma cells." (PMID 31382593, 2019). "HIF-1α has been suggested to interplay with Wnt signaling components in order to activate a neuronal differentiation process in both normal brain and glioblastoma (GBM)." (PMID 31410187, 2019). "Inhibition of TRPC6, by shRNA or expression of its dominant-negative mutant (DNC6), abolished hypoxia-induced HIF-1α protein accumulation in U251 human glioblastoma cells via promotion of HIF-1α hydroxylation." (PMID 30691160, 2019). "Li and colleagues showed that PTEN negatively regulates PTEN/HIF-1α angiogenic pathway in glioblastoma." (PMID 31366089, 2019). "In the U251 glioblastoma cells, campothecins (CPTs) analogues can inhibit the accumulation of HIF1α protein." (PMID 30943920, 2019). "Recent evidence shows that the hypoxia master regulator HIF-1α can induce lncH19 transcription in glioblastoma." (PMID 30781795, 2019). "These authors showed that FAT1 is associated with HIF-1α expression, as well as with its targets PGK1 (Phosphoglycerate kinase 1) and VEGFA in human glioblastoma samples." (PMID 31010154, 2019). "In glioblastoma cells specifically, hypoxia induces and maintains stem cell characteristics, and HIF-1α has been shown to be involved in proliferation, migration invasion and radio- and chemoresistance." (PMID 29164272, 2018). "Experiments of miRNA over expression indicated that miR-675-5p in SW620 cells, promoted the activation of HIF1α pathway, this observation was consistent with our data obtained in glioblastoma." (PMID 28061476, 2017). "Intraperitoneal injections of DT significantly inhibited the growth of established glioblastoma xenografts, and suppressed expression of HIF-1α and carbonic anhydrase (CA9), a surrogate marker of hypoxia." (PMID 28410215, 2017).
glioblastoma (continued). "Low pHe was also shown to increase VEGF production in glioblastoma cells in a HIF-1α –independent, ERK1/2/AP-1-dependent manner." (PMID 28806945, 2017). "Incubation of glioblastoma cells with D11 induces cell death and upon hypoxia the compound leads to HIF-1α destabilization." (PMID 28045438, 2017). "Our data show that incubation of glioblastoma cells with D11 results in rapid HIF-1α destabilization and impaired transcriptional activity." (PMID 28045438, 2017). "Taken together, these results suggest that DT at clinically achievable concentration functions as an inhibitor of HIF-1α, worthy of further investigations in the therapy of glioblastoma." (PMID 28410215, 2017). "Recently, we demonstrated in vitro and in vivo, in a model of glioblastoma, that miR675-5p works as a hypoxia mimetic factor while its inhibition reduces tumour growth by affecting HIF1α stabilization." (PMID 28061476, 2017). "HET0016 is also shown to decrease MAPK signaling, pSTAT1, EGFR, and HIF-1α in glioblastoma (GBM) tumor lysates." (PMID 29292756, 2017). "Here we report that hypoxia significantly stimulated H19 expression in glioblastoma cell lines, which was related to hypoxia-inducible factors 1α (Hif-1α)." (PMID 28327666, 2017). "We compared the localization of SOX2+ HIF-1α+ RNApII-S2P-/low cells with that of HIF-2α+ cells in serial sections of glioblastoma tissues." (PMID 26799577, 2016). "First, the expression of SOX2, NANOG, HIF-1α, and RNApII-S2P in glioblastoma tissue was investigated by single-color immunohistochemistry." (PMID 26799577, 2016). "High levels of nuclear localized HIF-1α are observed in the majority of glioblastomas and anaplastic astrocytomas, particularly surrounding areas of necrosis in glioblastomas, and expression levels correlated with gliomal tumor grade." (PMID 26689994, 2016). "Taken together, these data imply that the “peri-necrotic niche” harboring HIF-1α+ quiescent stem-like tumor cells in glioblastoma tissues can be generated in an intratumoral gradient of hypoxia and is associated with an enhanced tumorigenic capacity." (PMID 26799577, 2016). "This zone containing NANOG+ HIF-1α+ RNApII-S2P-/low cells is considered a model corresponding to the “peri-necrotic niche” in glioblastoma tissues." (PMID 26799577, 2016). "The NOX4-mediated ROS are known to contribute to cycling hypoxia-promoted tumor progression with activation of HIF-1α in glioblastoma cells and xenografts." (PMID 27043542, 2016). "By culturing glioblastoma cell spheroids under hypoxic conditions, we showed that HIF-1α+ quiescent stem-like cells emerge in a hypoxia-dependent manner and are associated with an enhanced sphere-forming activity." (PMID 26799577, 2016). "To further evaluate the association of these cells with large ischemic necroses in glioblastoma tissues, we measured the frequency of SOX2+ HIF-1α+ RNApII-S2P-/low cells and compared it with the extent of necrosis in 21 cases of glioblastoma." (PMID 26799577, 2016). "We also analyzed the frequency and localization of tumor cells showing immunophenotypes other than SOX2+ HIF-1α+ RNApII-S2P-/low in the representative glioblastoma cases (n = 3)." (PMID 26799577, 2016). "SOX2+ HIF-1α+ RNApII-S2P-/low cells were found, albeit at a low frequency, in glioblastoma tissues around large ischemic necroses." (PMID 26799577, 2016). "Results of the model suggest a novel observation: feedback from IGFBP2 to HIF1α is integral to the sustained growth of glioblastoma." (PMID 25884993, 2015). "This study offers an explanation for the difficulties encountered by current drugs targeting IGFIR to reduce glioblastoma cell growth: a secondary mechanism that upregulates HIF1α." (PMID 25884993, 2015). "The ability of the anti-S1P mAb to inhibit HIF-1α accumulation was tested in two other models, including the lung adenocarcinoma cell line A549, and the glioblastoma cell line U87." (PMID 25915662, 2015).